ENSG00000212445
Synonyms: LOC124900379
Gene: Small nucleolar RNA gene on chromosome 16 (68,189,287 to 68,189,421, forward strand). Ensembl gene ENSG00000212445.
Gene Ontology:
Biological process: RNA processing
Cellular component: nucleolus
Homologues: Paralogues in human: SNORA48 (86% identical), SNORA48B (81% identical).